IL4 (interleukin 4)
Diseases named in the same sentence as IL4 in open-access papers (continued):
Sharing a sentence is not in itself a finding about the gene and the disease.
metabolic disease (18 papers, 2014 to 2025). A congenital disorder (due to inherited enzyme abnormality) or acquired (due to failure of a metabolically important organ) disorder resulting from an abnormal metabolic process. "The results showed that decreased metabolic disorder in recipient mice was accompanied by a significant elevation of Th2-type cytokines, including IL-4, IL-5, IL-6, IL-10, and IL-13." (PMID 38195424, 2024). "Because GPS2 expression, and thereby corepressor complex function, in tissue macrophages is altered in immuno-metabolic disease contexts in humans, our study should stimulate the further investigation of IL4 signaling in human macrophage subtypes." (PMID 36610795, 2023). "Anti-inflammatory cytokines (adiponectin, transforming growth factor-β, IL-4) were produced from the adipose tissue of lean persons with active mitochondria, and they mediated physiological functions instead of metabolic diseases." (PMID 35209178, 2022). "There is a clear association between the inflammatory biomarkers used to calculate the DII score (CRP, IL-1β, IL-6, TNF-α, IL-4, and IL-10) and cardio-metabolic diseases such as obesity, diabetes, or CVD." (PMID 27527152, 2016). "In fact, a number of systematic reviews have shown the association between inflammatory biomarkers, such as CRP, IL-1β, IL-6, TNF-α, IL-4, or IL-10, and cardio-metabolic diseases." (PMID 27527152, 2016). "The elevated circulating IFN-γand IL-4 levels support the hypothesis that these children may face higher metabolic disorders and allergy disease risks in later life." (PMID 34836513, 2021).
respiratory disease (16 papers, 2012 to 2025). "However, the induction of TH2 cytokines such as IL-4, IL-5 and IL-13 has been associated with vaccine-associated enhanced respiratory disease (VAERD), a set of diseases with predominant involvement of the lower respiratory tract." (PMID 35287350, 2022). "The induction of CD4+ type 2 helper T-cell (Th2) (IL4, IL5, or IL13) responses has been associated with vaccine-associated enhanced respiratory disease (VAERD), as seen in some patients with respiratory virus infections." (PMID 36685587, 2022). "The Th1/Th2 balance has been recognized as an important factor among vaccine researchers because vaccine-associated enhanced respiratory disease (VAERD) is largely associated with low-titer neutralizing antibodies and Th2-biased immune responses (related to IL-4 and IL-13 cytokines)." (PMID 35632468, 2022). "Levels of IL-4, IL-5, IL-13, and eotaxin followed the pattern established in the previous study and correlated inversely with antibody levels and directly with pulmonary eosinophilia as previously reported for other respiratory diseases." (PMID 36560488, 2022). "Various cytokines, such as IL2, IL4, IL6, IL8, and TNFα, and other inflammatory markers, such as intercellular adhesion molecule (ICAM) 1, soluble P-selectin, and CRP, have previously been associated with metal exposure or respiratory diseases." (PMID 25272992, 2014). "IL-4 suppresses the transcriptional activity of all the inflammatory cytokines and plays an important role in regulation of inflammatory activity of pig alveolar macrophages in respiratory disease conditions." (PMID 22340040, 2012). "We found that T CD4+/IL-4+ and T CD4+/IL-10+ populations were highly increased in the RS group, and our results are consistent with these reports, suggesting that chronic stress might be promoting lung susceptibility to infectious and respiratory diseases." (PMID 41155294, 2025).
neurodegenerative disease (14 papers, 2017 to 2026). A disorder of the central nervous system characterized by gradual and progressive loss of neural tissue and neurologic function. "Specifically, IL4 and GATA2 are associated with oxidative phosphorylation and multiple neurodegenerative disease pathways, suggesting a potential synergistic or complementary role in energy metabolism and nerve cell function." (PMID 41481554, 2026). "HBOT increased the production of IL-4 and IL-13 to exert the anti-inflammatory effects in spinal cord injury and neurodegenerative diseases, respectively." (PMID 34440146, 2021). "It was previously found that the IL-4 and IL-13 signaling pathways play a neuromodulating role by regulating the oxidative stress in AD and other neurodegenerative diseases." (PMID 32382304, 2020). "The IL-4/IL-4Rα-Nrf2 axis maybe the potential targets for the development of novel therapies for neurodegenerative diseases." (PMID 36539414, 2022). "Our findings suggest IL-4 might be a new modulator for Nrf2 to treat neurodegenerative diseases." (PMID 36539414, 2022). "Interestingly, microglia activation by IL4 has been described to promote neuroprotective and neurorestorative effects, which might be important to slow the progression of neurodegenerative diseases." (PMID 28337124, 2017).
neurological disorders (14 papers, 2014 to 2025). "Although multiple cytokines (IL-4, IL-10, etc.)together inhibited neuroinflammation in neurological disorders, their functions were significantly different." (PMID 40134421, 2025). "COX-2, increased IL-10 and TGF-β1 in the brain tissue of rats and reduced plasma cytokines TNF-α, IL-1β, IL-2, IL-3, IL-4, IL-5, IL-6, etc. and exotoxin activity in plasma of different neurological disorders." (PMID 40297338, 2025). "IL-4, which is secreted by T helper 2 cells, is crucially involved in higher brain functions, including spatial memory, learning, and neurological disorders." (PMID 35153973, 2021). "Our results highlight the preponderant role, at the expression level, of IL-17 and regulatory markers IL-4, IL-10, and Foxp3 in the blood as the major contributors to the segregation of the two studied neurological disorders." (PMID 33719347, 2021). "Increasing evidence shows that IL-4 plays a well-established role in attenuating inflammation in neurological disorders." (PMID 32982939, 2020). "The parameters that distinguished MS patients from patients with other neurological disorders were IgG intrathecal synthesis, the IgG index and its correlation with CSF IL-4 levels." (PMID 26317430, 2015). "The parameters that distinguished MS patients from patients with other neurological disorders were the intrathecal IgG synthesis, the IgG index and the correlation between the IgG index and CSF IL-4 levels." (PMID 26317430, 2015). "As a T cell-derived mediator, IL-4 plays a critical role in several neurological disorders." (PMID 32982939, 2020). "Moreover, IL-4 in particular was shown to regulate brain immunity, with positive effects on neurological disorders." (PMID 33096789, 2020). "Among peptides active in neurological diseases, a fragment of NCAM protein, named FGL peptide, induced the secretion of IL-4 from microglial cells leading to the increase of CD200 and to the inversion of the age related decline of hippocampus in vivo." (PMID 30208640, 2018).
renal diseases (14 papers, 2013 to 2026). "Th2 cytokines such as IL-4 and IL-13 are involved in renal diseases (podocyte disorders) that cause proteinuria, such as minimal change nephrotic syndrome (MCNS)." (PMID 40191205, 2025). "Notably, Th2 cytokines, such as IL-4 and IL-13, as well as neutrophil- and macrophage-mediated inflammation, are also implicated in the progression of renal diseases, contributing to glomerular injury, proteinuria, and chronic kidney inflammation." (PMID 40191205, 2025). "As some reports have found IL-4 to play a significant role in enhancing the recovery of tubular damage in renal disease by inducing M2 macrophage phenotypic polarization." (PMID 38662181, 2024). "The increase in expression of IL4, 10, 13, and 14 and the pathway identification of chemokine receptors bind chemokines would appear to have consequences for renal diseases in the human setting due to their role in immune responses and inflammation." (PMID 36982180, 2023). "Interleukin (IL)-4 has been shown to be an important factor in modulating the recovery of tubular injury in renal disease." (PMID 32174845, 2020). "Interleukin, the multifunctional inflammatory cytokines are closely associated with various renal diseases and the injury of kidney residential cells, such as IL-6, CXCL8, IL-1β, IL-2 and IL-4." (PMID 32765640, 2020). "The increment induced by IL-4 in lymphocytes of other renal diseases was more than that in the lymphocytes of healthy controls (P = 0.007) or IgAN (P = 0.022)." (PMID 25647400, 2015). "Donizetti-Oliveira reported that ASC treatment prevents renal disease mostly because of the inflammatory response which increases the expression of anti-inflammatory factors IL-4, IL-10." (PMID 24260375, 2013). "The contributions of Th2 response to renal disease activity and LN development include the IL-6 and IL-4 production by activated basophils, which leads to autoantibody deposition in the kidney, increasing in a positive feedback loop the Th2 response, and B cell activation." (PMID 35005031, 2021). "We identified six genes enriched to kidney diseases and ccRCC (AR, DPP6, GNB3, IL4, SAA1, SEMA3G)." (PMID 35565241, 2022). "What is more, B cells from IgAN patients seem to be more sensitive to IL-4 because the decrease in C1GALT1C1 mRNA level induced by IL-4 was higher in IgAN B cells than in lymphocytes of both healthy children and children with other renal diseases." (PMID 30406499, 2019). "This experimental study was performed in vitro on cultured B lymphocytes from children with IgAN, treated or not with interlukin-4 (IL-4) or 5-aza-2’-deoxycytidine (5-Aza-dC, AZA); the IgAN lymphocytes were compared to lymphocytes from children with other renal diseases or from healthy children." (PMID 25647400, 2015).
psychiatric disorder (13 papers, 2008 to 2026). A disorder characterized by behavioral and/or psychological abnormalities, often accompanied by physical symptoms. "According to the “protective immunosurveillance” model, increased susceptibility to mental illness may result from a deficiency in circulating T cells and the IL-4 they can produce, as the IL-4 mediates processes which are able to counteract neuroinflammation and restore brain homeostasis." (PMID 23382717, 2013). "The relationship between IL-17 and IL-4 in mental illness is controversial." (PMID 40292283, 2025). "Inflammatory cytokines or other inflammatory stimuli (e.g., IL-1β, IL-4, IL-6, TNF-α, and MCP-1) induce depressive symptoms or other psychiatric disorders, and these factors may also predict the development of these disorders." (PMID 33536923, 2020).
adenocarcinoma (12 papers, 2009 to 2025). A common cancer characterized by the presence of malignant glandular cells. "Recently, we have linked the expression of galectin-3 on the A549 epithelial cell line –an adenocarcinoma, to the activation of human basophils for the release of histamine and secretion of IL-4 and IL-13." (PMID 33154744, 2020). "However, we recently reported evidence for a unique mode of IgE-dependent activation in basophils whereby these granulocytes released histamine and secreted large quantities of IL-4/IL-13 when co-cultured with the A549 epithelial cell (EC) line –an adenocarcinoma of lung origin." (PMID 33154744, 2020). "In a long-term study (8 months) of rats, the highest levels of IL-4 and TNF-α were found in the groups that showed the lowest numbers of adenocarcinomas in response to DMH induction." (PMID 19660118, 2009).
lung (11 papers, 2004 to 2024). "Previous studies found that the activation of the PI3K/Akt signaling pathway during liver ischemia-reperfusion injury, increased IL-4, and IL-10 expressions, decreased IL-1β and TNF-α expressions, and reduced the hepatic inflammatory response." (PMID 36835571, 2023). "In turn, IL-4/IL-13-induced AAM upregulate Ear11 production and inducing IL-25-dependent lung neutrophilia." (PMID 32457448, 2021).
heart disease (7 papers, 2019 to 2023). "In this review, the pathophysiological effects of interleukins including the IL-1 family (IL-1, IL-18, IL-33, and IL-37), IL-2, IL-4, the IL-6 family (IL-6 and IL-11), IL-8, IL-10, and IL-17 on primary cell types of heart disease is elucidated." (PMID 37047468, 2023). "The role of IL-4 in the development of heart disease is complex, and it has been shown to have both beneficial and adverse effects in preclinical studies." (PMID 35654493, 2022). "This review will primarily focus on the pathophysiological effects of various interleukins including the IL-1 family (IL-1, IL-18, IL-33, IL-37), IL-2, IL-4, the IL-6 family (IL-6 and IL-11), IL-8, IL-10, IL-17 on primary cells of heart disease-CMs, FBs, ECs, and immune cells." (PMID 37047468, 2023). "Therefore, we tested the subtypes of Th1 (CD4+IFNγ+), Th2 (CD4+IL4+), and Treg (CD4+CD25+Foxp3+) cells, which influence inflammation associated with heart disease." (PMID 31547872, 2019). "Other cytokines (TNF-alpha, IL-4, IL-17, IFN-gamma, CCL2, and IL-10) have shown differences between severe chagasic heart disease and the undetermined stage but not between the different stages of chagasic heart disease progression." (PMID 32455143, 2020).
gastrointestinal tumors (4 papers, 2022 to 2025). "IL-4 promotes the production of H2O2, which induces DNA damage in malignant gastrointestinal tumors." (PMID 35680568, 2022).
gastrointestinal disorders (3 papers, 2022 to 2024). "Interestingly, previous studies reported an increase in IL-4 concentrations in humans and mice affected by food-induced gastrointestinal disorders." (PMID 35867776, 2022).
overlap syndrome (3 papers, 2017 to 2025). "In vitro studies demonstrate that IL-4 stimulation alone induces the conversion of IgG to IgG4, significantly increasing plasma IgG4 concentrations, and IgG4 ANCA subtypes in individuals with overlap syndrome." (PMID 41181091, 2025).
peripheral neuropathy (3 papers, 2022 to 2023). A disorder affecting the peripheral nervous system. "The prevention of chemotherapy-induced peripheral neuropathy is correlated with the active IL-4/STAT6 signaling pathway." (PMID 35273508, 2022). "Therefore, the reduced sign of peripheral neuropathy in mice on administration of ARH was evident by significant increase in plasma levels of IL-4." (PMID 35273508, 2022). "We observed that non-treated peripheral neuropathy increased the expression of IL-1β proinflammatory cytokines in the nerve and DRG, as well as decreasing the expression of the anti-inflammatory cytokines IL-4 and IL- 10 in the nerve, corroborating previous studies." (PMID 37175503, 2023).
retinopathy (3 papers, 2012 to 2022). "IL-4 and TNF were also significantly increased in this group compared to the T2D without retinopathy group." (PMID 35692536, 2022).
endocrine disorders (2 papers, 2018 to 2024). "It seems that regulating the immune system and suppressing pro-inflammatory pathways like tumor necrosis factor-α and interleukin-6 or triggering anti-inflammatory pathways like interleukin-4 and 10 may be one of the potential mechanisms in the managing of endocrine disorders." (PMID 38504163, 2024).
vasculopathy (1 paper, 2018). "In endothelial cells, IL-4 suppresses VE-cadherin expression and reduces vascular integrity, which is a characteristic feature of SSc vasculopathy." (PMID 29415756, 2018).
IL4 also shares sentences with these, for which no sentence is quoted: chronic periodontitis (17 papers); chronic sinusitis (9); chronic rhinosinusitis with nasal polyps (6); liver cirrhosis (6); pneumonitis (6); rectal cancer (5); diphtheria (4); end-stage renal disease (4); eosinophilic granulomatosis with polyangiitis (4); hematologic disease (4); spinal cord injury (4); viral disease (4); Abdominal obesity (3); Acute hepatitis (3); acute lung injury (3); chronic spontaneous urticaria (3); developmental delays (3); diabetic retinopathy (3); esophagitis (3); head and neck cancer (3); mood disorder (3); Multiple Organ Failure (3); myeloproliferative disease (3); neurodevelopmental disorder (3); pulmonary hypertension (3); respiratory syncytial virus infection (3); Shock (3); acute bronchiolitis (2); acute coronary syndrome (2); acute myocardial infarction (2).
A further 274 diseases each share a sentence with IL4 in 2 papers or fewer.